RAC1 (Rac family small GTPase 1)
Diseases named in the same sentence as RAC1 in open-access papers (continued):
Sharing a sentence is not in itself a finding about the gene and the disease.
ovarian carcinoma (continued). "Thus, the results presented here define a critical scaffolding role for Hax-1 in LPA-stimulated Rac1-cortactin interaction and subsequent ovarian cancer cell migration." (PMID 25053987, 2014). "Furthermore, it has recently been shown that activation of the PI3K/Akt pathway, known to be upstream of Rac1 and Cdc42 activity, positively correlates with uPA expression in an ovarian cancer cell line." (PMID 20067638, 2010). "Finally, our experiments showed that MIIP could reduce MMP9, which is consistent with the recent report of Rac1/Pak1/p38/MMP axis in ovarian cancer oncogenesis." (PMID 27760566, 2016). "DOCK7 has also been reported to be highly expressed in ovarian cancer, and is recruited into the nucleus by MDC1 to participate in the DNA damage response through the RAC1/CDC42/PAK1 module." (PMID 38385857, 2024). "In ovarian cancer cells, silencing of MICALL2 greatly suppressed Rac1 activation, whereas MICALL2 overexpression exerted the opposite effect." (PMID 38203692, 2023). "To investigate the specific mechanism by which TBC1D2 promotes ovarian cancer progression, we studied at first if TBC1D2 modulates OC cell migration and invasion through regulating RAC1 and IQGAP1." (PMID 35574392, 2022). "After the knockdown of fascin in ovarian cancer stromal cells with high fascin expression, we found that CSC activity, metastasis, and the EMT were reduced through pathways such as Rac1, RhoA, and NF-κB." (PMID 36355541, 2022). "In terms of Rac-1 inhibitor, R-ketorolac has been approved by FDA which suppresses adhesion, migration, and invasion of ovarian cancer cells." (PMID 33490663, 2021). "The treatment inhibited the actin-bundling into stress fibers as well as ovarian cancer cell migration by reducing GTP-bound Cdc42 and Rac1, further indicating a therapeutic role of G2 in ovarian cancer." (PMID 34830909, 2021). "Since the related RAC1 is an activator of MEK-ERK signaling, e.g., in ovarian cancer cell EMT, the functional antagonism between RAC1 and RAC1B extends to the level of individual MAPK pathways." (PMID 33266416, 2020). "Rac1 and Cdc42 are highly expressed in EOC and therefore inhibitors of these two GTPases have undergone research on primary human ovarian cancer cells." (PMID 32443784, 2020). "In ovarian cancer, a recently described tripartite complex that includes the SOS1 GEF is essential for LPA-mediated Rac1 activation and metastasis." (PMID 30261690, 2018). "Activation of Rac1 by the Tiam1 or PREX1 GEF proteins is spatially distinct in the cell and dictates anti- or pro-migratory responses in ovarian cancer cells." (PMID 30261690, 2018). "Rac1-dependent functions in EMT, stem cell phenotypes, angiogenesis and chemoresistance all have high relevance to ovarian cancer." (PMID 30261690, 2018). "However, given the low frequency of Rac1 missense mutants (0.01–0.02% for G15, C18) such rare mutations would be undetectable in the sample size and should not be taken as lack of evidence for the importance of Rac1 in ovarian cancer." (PMID 30261690, 2018). "In ovarian cancer cells, p70-S6K1 regulates cytoskeleton organization and cell migration by activating the GTPases Rac1 and Cdc42, involved, respectively, in dictating forward movement and migration’s direction." (PMID 27491285, 2016). "Consistent with high Rac1 activity, silencing of IQGAP1 expression in fibroblasts, osteosarcoma cells and ovarian carcinoma cells lead to unconstrained membrane protrusion and disrupted directional cell migration on fibrillar extracellular matrices." (PMID 24355937, 2013). "Numerous previous studies have shown that FDPS is strongly associated with tumor drug resistance (For example, FDPS modulates platinum sensitivity in human ovarian cancer; Disruption of the FDPS/Rac1 axis increases the sensitivity of radiation therapy for pancreatic ductal adenocarcinoma)." (PMID 40839681, 2025).
ovarian carcinoma (continued). "Lysophosphatidic acid (LPA) activates Ras, which activates RAC1 to induce lamellipodia formation in metastatic ovarian cancer cell lines but not in non-metastatic cell lines." (PMID 39354505, 2024). "Ovarian cancer cells secrete transforming growth factor beta (TGFβ) which binds to the TGFβ receptors on the mesothelial cells, which then activate the Rac Family Small GTPase 1/SMAD (RAC1/SMAD) signaling pathway." (PMID 31640297, 2019). "Similar to the ovarian cancer patients, RAC1b expression was not mutually exclusive and 152/157 (97%) of the metastatic colorectal patients had higher canonical RAC1 than RAC1b expression." (PMID 30261690, 2018). "Our results are similar to the previous research that EGFR is reported to overexpressed in most ovarian cancer, and the activation of the EGFR pathway has impact on invasion and metastasis as well as cell survival through the MAPK/ERK, PI3K/AKT and Rac1 pathways." (PMID 29510732, 2018). "Although specific mechanisms of Rac1 activation by VEGF have not been explored in ovarian cancer models, there is abundant evidence that Rac1 is a component of VEGF signaling to angiogenesis." (PMID 30261690, 2018). "The selected illustrations do not capture the entire scope of potential ovarian cancer TME regulation of Rac1 activity." (PMID 30261690, 2018). "Our results also indicate that the competitive inhibition of the interaction between endogenous Hax-1 and Rac1 or Hax-1 and cortactin by the ectopic expression of any of these domains led to a decrease in LPA-stimulated migration of ovarian cancer cell line SKOV3." (PMID 25053987, 2014). "Moreover, it has been proven that MEL activates the death receptors and inhibits the JAK2L/STAT3 pathway, leading to the inhibition of ovarian cancer cell growth; it can also decrease the expression levels of p-AKT and ERK1/2, and suppress the Rac1-dependent pathway." (PMID 35268753, 2022). "We reported previously that R-ketorolac, but not the S-enantiomer, inhibited Rac1 and Cdc42-dependent downstream signaling, growth factor stimulated actin cytoskeleton rearrangements, cell adhesion, migration and invasion in ovarian cancer cell lines and patient-derived tumor cells." (PMID 33413202, 2021). "Taken together, our identification of R-ketorolac as a Rac1/Cdc42 GTPase inhibitor may help to explain the apparent benefits of racemic ketorolac in human breast and ovarian cancer patient survival, and why other NSAIDs have not yielded comparable findings." (PMID 31344967, 2019).
glioblastoma (65 papers, 2009 to 2025). The most malignant astrocytic tumor (WHO grade IV). "In glioblastoma, the increased activity of Rac1, Cdc42, RhoA, and RhoG is associated with the invasiveness of tumor cells." (PMID 35053605, 2022). "To further explore the mechanisms that mediate RhoG-regulated glioblastoma cell invasion, we examined the role of RhoG in the formation of two structures that have been implicated in Rac1-regulated cell migration and invasion: invadopodia and lamellipodia." (PMID 22966858, 2012). "Here we report that human Mena (hMena) colocalizes with Rac1 in lamellipodia, and using an unmixing assisted acceptor depletion fluorescence resonance energy transfer (u-adFRET) analysis that hMena associates with Rac1 in vivo in the glioblastoma cell line U251MG." (PMID 19277120, 2009). "For example, in an analysis of a set of erlotinib-resistant GBM cell lines in an expression analysis of 244 prospectively selected genes, Rac1 expression was shown to associate significantly with erlotinib-resistant glioblastoma." (PMID 25243137, 2014). "In astrocytes and glioblastoma cells RhoGDI1 interacts with the cytoplasmic domain of the β8 integrin subunit of the αvβ8 heterodimer, which limits the activity of Rac1 and Cdc42." (PMID 39086660, 2024). "We previously demonstrated that Rac1 is activated upon Sema3C binding to its receptor complex, and Rac1 is an essential mediator of Sema3C-dependent glioblastoma progression." (PMID 37080989, 2023). "To begin evaluating the possible impact of 1A-116 treatment in glioblastoma, we first analyzed Rac1 mRNA expression levels and its prognostic role in patient survival and outcome using publically available datasets." (PMID 36230732, 2022). "We found that targeting Rac1 inhibits cell proliferation and cell cycle progression using different in vitro human glioblastoma models." (PMID 36230732, 2022). "The Rho family of GTPases from the Ras superfamily, Rho-A, Rac1, and Cdc42, are responsible for the spatial regulation of glioblastoma invasion." (PMID 35053605, 2022). "Paulino and colleagues affirmed the intracellular region of TROY activated Rac1 by binding to adapter protein Pyk2 to promote the migration and invasion of glioblastoma cells." (PMID 35646083, 2022). "This work highlights the opportunity to exploit a chronotherapeutic approach with an agent that blocks Rac1 interaction with its GEFs, providing promising results to tackle glioblastoma, an aggressive cancer with extremely limited therapeutic options." (PMID 34371781, 2021). "For example, U87MG glioblastoma cells are strictly mesenchymal mode cells, and Rac1 signaling inhibition blocks their movement." (PMID 34440861, 2021). "For example, CFIm25 causes 3′UTR shortening of a number of genes in glioblastoma cells and promotes tumor suppression; however, CSTF2 in urothelial carcinoma of the bladder elicits 3′UTR shortening of RAC1 and contributes to UCB pathogenesis." (PMID 33648552, 2021). "Our results should be taken into consideration in future preclinical studies for glioblastoma treatment, as well as in all studies related to GEFs and the RAC1 signaling pathway." (PMID 34371781, 2021). "TWEAK is also expressed by glial cells in the central nervous system, implying the presence of TWEAK signaled Rac1-dependent glioblastoma invasion." (PMID 32089990, 2020). "TRPV4 promotes Rac1 activity in glioblastoma U87 cells leading to increased cell migration through TRPV4-dependent Akt phosphorylation/activation." (PMID 33240883, 2020). "DOCK180 is a Rac1 guanine nucleotide exchange factor (GEF) and is also downstream of other RTKs such as MET, forming a complex with several other proteins and driving Rac1-dependent glioblastoma cell movement." (PMID 32089990, 2020). "The genetic profile of glioblastoma cells shows that most of them have more than one copy of chromosome 7, on which the Rac1 gene is located." (PMID 32089990, 2020).
glioblastoma (continued). "Time‐lapse imaging of Rac1 activity over several days has revealed that Rac1 activity in glioblastoma cells fluctuates over a timescale, substantially longer than that of the replication cycle." (PMID 32270554, 2020). "Rac1 and Cdc42, which promote actin polymerization, are activated in glioblastoma cells invading into the brain parenchyma." (PMID 32270554, 2020). "The Rho family of small GTPases, which includes Rac1, Cdc42, and RhoA, is an important family whose members are key regulators of the invasion and migration of glioblastoma cells." (PMID 32089990, 2020). "When glioblastoma cells were embedded in gel, the high Rac1 activity cell population was found to invade into the gels, leading the other cells." (PMID 32270554, 2020). "In glioblastoma, patients with a low survival rate had higher expression of Trio, Ect2 and Vav3, as well as high Rac1 expression." (PMID 32322580, 2020). "According to a biosensor assay done on glioblastoma cells, low Rac1 and low Cdc42 are found on the trailing end while high Rac1 and high Cdc42 levels are found on the leading edge of the cells." (PMID 32089990, 2020). "Rac1, Rac2 and Rac3 promote cell proliferation of glioblastoma cells that form tumor spheres, while these colonies are reduced in number and size by silencing either Rac GTPase." (PMID 31514269, 2019). "More important, we confirmed that NKCC1 accelerates EMT in glioblastoma cells via NKCC1‐dependent Rac1/RhoA activation." (PMID 30159893, 2019). "Silencing of either Rac1, Rac2 or Rac3 also inhibits glioblastoma cell migration and invasion in vitro." (PMID 31514269, 2019). "It was later reported that EGFRvIII, a constitutively active EGFR mutant, stimulates the phosphorylation of Dock180 via Src, which stimulates Rac1 signaling, glioblastoma cell survival, and migration." (PMID 30544910, 2018). "Overexpression of the Rac1 GEF DOCK180 drives glioblastoma invasion through the activation of a Rac1-dependent kinase pathway." (PMID 30261690, 2018). "This is consistent with a report that a Rac1 inhibitor (equivalent of RCC2 overexpression) increased the sensitivity of glioblastoma cell lines to Camptothecin." (PMID 29321004, 2018). "Most recently, it was shown that EGFR overexpression or expression of EGFRvIII stimulates Rac1 activation and promote glioblastoma cell migration through activating the MLK3-JNK signaling axis." (PMID 30544910, 2018). "Specifically, the SEMA ligand SEMA3C controls glioblastoma stem cell survival though RAC1 activation, suggesting that the effect of SEMA genes on brain tumor stem cells is cell context specific." (PMID 29377567, 2018). "On the other hand in glioblastoma, loss of SEMA5A leads to Rac1 activation resulting in increased invasiveness, indicating that SEMA5A suppresses motility of cell." (PMID 30577767, 2018). "In our zebrafish transplantation model, we also observed a role of not only Rac1, but also Rac2 and Rac3 in angiogenesis induced by glioblastoma tumorspheres." (PMID 28160553, 2017). "Here we demonstrated that not only Rac1 but also Rac2 and 3 are required for the growth, migration and invasion of glioblastoma stem-like cells." (PMID 28160553, 2017). "Suppression of Rac1 expression in glioblastoma cell lines and human primary glioblastoma induce apoptosis but not in normal primary human adult astrocytes." (PMID 28160553, 2017). "In conclusion, not only Rac1 but also Rac2 and 3 are important for glioblastoma tumorigenesis and can serve as the potential therapeutic targets against glioblastoma and its stem-like cells." (PMID 28160553, 2017). "In summary, Rac2 and 3 along with Rac1 are required for cell migration and invasion in glioblastoma stem-like cells." (PMID 28160553, 2017). "Other Rho-family GTPases have not yet been examined, but RhoG merits consideration since it has been reported to stimulate membrane ruffling and macropinocyctosis and can activate Rac1 in response to EGF or HGF in glioblastoma cells." (PMID 25762935, 2015).
glioblastoma (continued). "In search of a mechanism for the contribution of RhoG to the malignant behavior of glioblastoma cells, we found that depletion of RhoG strongly inhibits activation of the Rac1 GTPase by both HGF and EGF." (PMID 22966858, 2012). "Here, we show that depletion of RhoG significantly inhibits both HGF- and EGF-stimulated Rac1 activation in glioblastoma cells, demonstrating that RhoG acts upstream of Rac1 in these cells." (PMID 22966858, 2012). "We observed that depletion of RhoG strongly inhibits glioblastoma cell colony formation, similar to the extent of depleting Rac1, indicating a significant role for RhoG in glioblastoma cell survival." (PMID 22966858, 2012). "δ-Catenin knockdown in U87 glioblastoma cell decreased cell proliferation, invasion and Rac1 activity." (PMID 22151302, 2011). "The relative levels of Rac1 and Rac3 in PCa are similar to what has been shown in glioblastoma cells." (PMID 21776386, 2011). "Moreover, TWEAK induces in glioblastoma cell lines sequential activation of the Rho GTPase Cdc42 and Rac1 along with Rac1-dependent cell migration." (PMID 36339601, 2022). "Furthermore, the inhibition of RAC1 resulted in the inhibition of proliferation in cultured human glioblastoma cells, suggesting a significant role for RAC1 in the pathogenesis of human glioblastoma." (PMID 34943902, 2021). "Furthermore, when this drug combination was extended by an inhibitor of RAC1, the migratory activity of different glioblastoma cells was even more strongly reduced." (PMID 34959641, 2021). "Moreover, the TWEAK-Fn14 signaling discussed previously stimulates RhoG-dependent Rac1 activation and subsequently rebuts lamellipodium formation and enhances the invasive behavior of glioblastoma." (PMID 32089990, 2020). "Furthermore, RhoG-specific exchange factor SGEF mediates RhoG activation, which in turn activates Rac1 in glioblastoma cells." (PMID 32089990, 2020). "Additionally, DOCK 7 is reported to play a critical role in the invasive behavior of the glioblastoma and mediates Rac1 activation following HGF stimulation." (PMID 32089990, 2020). "Trio mediates Rac1 activation following TWEAK stimulation in glioblastoma cells." (PMID 32089990, 2020). "For example, in addition to Rac1, Rac2 and Rac3 knockdown in glioblastoma stem cells showed a dramatic decrease in their invasive and migrative capabilities, confirming that Rac proteins in general do play a crucial and necessary role in the invasion of GBM cells." (PMID 32089990, 2020). "Rac1, Rac2 and Rac3 are required for the growth, migration and invasion of glioblastoma cells." (PMID 31514269, 2019). "To examine if Rac2 and Rac3, besides Rac1, also promote the migration and invasion of glioblastoma stem-like cells as they do in normal cells, we used the tumorspheroid cells derived from U251-MG that stably express shRNA or scramble shRNA to perform the cell migration assay using Transwell." (PMID 28160553, 2017). "To investigate whether Rac proteins can serve as therapeutic targets for glioblastoma, especially for GSCs or stemloids, we examined the potential roles of Rac1, Rac2 and Rac3 on the properties of tumorspheres derived from glioblastoma cell lines." (PMID 28160553, 2017). "In addition, plasma membrane localization of Rac1 in glioblastoma cells in situ indicates that Rac1 is constitutively active in a subset of these tumors." (PMID 22966858, 2012). "Thus, our observations that both RhoG and Rac1 significantly inhibit glioblastoma cell colony formation, identify these GTPases as such signaling nodes." (PMID 22966858, 2012). "Therefore, interference with this Rac1 gene might enhance the proliferation inhibition of erlotinib against glioblastoma." (PMID 25243137, 2014). "Consequently, Rac1 appears to be an ideal target for developing approaches to block glioblastoma." (PMID 23586025, 2013). "We therefore examined whether RhoG mediates HGF-induced Rac1 activation in glioblastoma cells." (PMID 22966858, 2012).